HIF1A (hypoxia inducible factor 1 subunit alpha)
Diseases named in the same sentence as HIF1A in open-access papers (continued):
Sharing a sentence is not in itself a finding about the gene and the disease.
cancer (continued). "Taken together, NRPas induced molecular regulation that led to cell death due to the deregulation of pro-apoptotic/anti-apoptotic proteins and, more importantly, by HIF-1α and Survivin down-regulation as well as by the inhibition of the cancer therapeutic key factor p38α." (PMID 40286084, 2025). "Interestingly, normoxic expression of HIF1α has been found in several cancer types, including CM, which constitutively harbors high levels of HIF1α." (PMID 39953610, 2025). "Currently, regulating HIF-1α activity has become an important strategy for the treatment of cancer." (PMID 41585262, 2025). "Summing up, the interplay between HIF-1α and Cai2+ is described mainly in cancer conditions." (PMID 40264757, 2025). "Therefore, the study of the therapeutic effects of the other active metabolites in the P. ginseng on cancer through HIF-1α offers broad research prospects." (PMID 41585262, 2025). "The significance of HIF-1α in the advancement of cancer is well recognized." (PMID 40244228, 2025). "Additionally, activation of antiapoptotic proteins and pathways occurs upon induction by HIF-1α, contributing to cancer cell survival and weakening the response to therapeutics—higher doses of the drug are tolerated by cells." (PMID 40710312, 2025). "Furthermore, therapeutic agents aimed at inhibiting HIF-1α signaling have been investigated for their efficacy in cancer treatment." (PMID 41311849, 2025). "HIF1α plays a critical role in many aspects of cancer biology." (PMID 41303712, 2025). "Research has indicated elevated expression of DTL in various cancer types and could operate as a HIF-1α-dependent effector within the hypoxia-triggered ISR axis, promoting tumor progression." (PMID 41409301, 2025). "We believe that this review, which triggers continuous research and exploration of whether other components in P. ginseng can play a therapeutic role in cancer through the HIF-1α pathway, will play an important role in cancer treatment." (PMID 41585262, 2025). "Cytokines, associated with cancer cell immuno-resistance, like TGF-β, IL-10 and IL-1β, were higher, while antitumor cytokines, including INF-γ, TNF-α and IL-2, were lower in PC lesions compared to normal tissues with a high HIF-1α expression." (PMID 39928285, 2025). "Thus, HIF-1α is considered an attractive target for cancer therapy, thereby making the development of strategies to inhibit HIF-1α activity and its associated pathways a high priority." (PMID 41514626, 2025). "Moreover, we found that 2-ANPC effectively downregulated HIF-1α at both the translational and transcriptional levels in the majority of cancer cells and promoted its proteasome-dependent degradation." (PMID 41514626, 2025). "Additionally, PRMT1 methylates and activates key transcription factors in critical signaling pathways, such as NF‐κB, STAT3, and HIF‐1α, therefore influencing cancer progression." (PMID 41256732, 2025). "More importantly, the metabolism reprogramming of cancer cells drives a shift in mitochondrial respiration toward glycolysis to obtain sufficient energy supply under hypoxia conditions, HIF-1α helps upregulate the expression of glycolysis key enzymes and glucose transporters in this process." (PMID 40775462, 2025). "However, it is well known that hypoxic conditions or activation of HIF-1α increase glucose concentration, aiding cancer cell proliferation." (PMID 40806771, 2025). "had previously reported that targeting HIF-1α could eradicate cancer stem cells in hematological malignancies." (PMID 40746567, 2025). "HIF-1a is a marker to identify aggressiveness and late-stage resistant cancer." (PMID 41305000, 2025). "Furthermore, HIF‐1α orchestrates metabolic reprogramming by favoring glycolysis for ATP production in cancer cells." (PMID 40227962, 2025). "Notably, HIF-1α increases reactive oxygen species levels in cancer cells by inhibiting the tricarboxylic acid cycle and activating the pentose phosphate pathway." (PMID 41514626, 2025).
cancer (continued). "Nevertheless, these results may constitute a starting point for further studies on the significance of the WWOX/HIF1A ratio in various types of cancer." (PMID 41007296, 2025). "Consequently, cancer cells undergoing metastasis cannot rely solely on oxygen-dependent regulation of PHD to maintain HIF1α stability." (PMID 40701956, 2025). "Cancer progression is also mediated by some transcription factors, such as HIF-1α." (PMID 40775462, 2025). "Beyond aiding oxygen delivery, HIF-1α drives cancer cell invasion and metastasis." (PMID 40507913, 2025). "In cancer, HIF-1α activation exerts a major influence on cellular metabolism." (PMID 41150799, 2025). "Additionally, HIF-1α facilitates metabolic reprogramming, enabling cancer cells to utilize anaerobic glycolysis even in oxygen-limited conditions." (PMID 39981236, 2025). "Hif-1α-positive cancer cells were found approximately 30-330 μm away from blood vessels." (PMID 39744223, 2025). "HIF1A stabilization can thus provide opportunities for early intervention in neoplastic VHL clones, and the VHL-HIF1A axis may be relevant for the development of resistance to the emerging class of PROTAC-based cancer therapies." (PMID 41420106, 2025). "In contrast, as reported in the literature for the capability of A3AR agonists to enhance HIF‐1α mRNA and protein expression in different cancers, our results show a reduction in HIF‐1α protein levels in A3AR antagonist‐treated PCa cells, likely supporting an A3AR‐dependent effect." (PMID 40181576, 2025). "In addition, we showed Hif1α overexpressing cancer cells were able to induce galactose metabolism while Myc overexpressing cancer cells did not." (PMID 40050422, 2025). "Thus, it can be envisioned that TRAP1 enables macrophages to install a pro-neoplastic transcriptional program orchestrated by HIF-1α independently of the hypoxic conditions found in the cancer regions furthest from blood vessels." (PMID 40877908, 2025). "Taken together, LDHA may increase lactate production to activate the signaling pathways which critical for cancer stemness, such as NF-κB, IL-8 and HIF-1α, and further regulate the CSC properties." (PMID 39930542, 2025). "Notably, inhibition of HIF1A has been recognized as a promising therapeutic strategy in various types of cancer." (PMID 40552073, 2025). "Overexpression of HIF-1A has been observed in various inflammatory disorders, cancer, and PE." (PMID 40804807, 2025). "Our study aimed to investigate whether the WWOX/HIF1A ratio affects the overall survival of patients, whether it allows for the identification of differences between cancer subtypes, and through which pathways it exerts its regulatory effects." (PMID 41007296, 2025). "Additional studies have shown that melittin downregulates oncogenic pathways, including Akt, NF-κB, hypoxia-inducible factor 1-alpha (HIF-1α), Wnt, and signal transducer and activator of transcription 3 (STAT3), further supporting its ability to interfere with cancer-associated signaling networks." (PMID 40871040, 2025). "Pharmacological targeting of HIF-1α is considered a therapeutic strategy for cancer treatment." (PMID 41585262, 2025). "WWOX and HIF1α were studied separately and extensively in many cancers." (PMID 41007296, 2025). "IL6 is known to stimulate aerobic glycolysis and HIF-1α in cancer cells." (PMID 38650935, 2024). "Additionally, HIF1α drives abnormal angiogenesis, further deteriorating blood perfusion and oxygenation, thus reinforcing a cycle of hypoxia and increasingly aggressive cancer behaviors." (PMID 39346906, 2024). "In summary, we demonstrated that MYH9 could stabilize HIF-1α and promote LR, glycolysis and cancer stemness in HCC." (PMID 39300073, 2024). "Moreover, because quercetin reduces β-catenin and HIF-1α stabilization, activates caspase-3, and inhibits Akt, mTOR, and ERK phosphorylation, it promotes cell viability loss, apoptosis, and autophagy in cancer." (PMID 39273552, 2024).
cancer (continued). "Under conditions of hypoxia, HIF-1α can upregulate the expression of PD-L1 in cancer cells." (PMID 38257813, 2024). "Hence, O-GlcNAc modification controls glycolysis in cancer cells and induces ER stress by modifying HIF-1α and its transcriptional target glucose transporter 1 (GLUT1)." (PMID 38732122, 2024). "Furthermore, HIF1A expression by E6 is differentially affected by HPV 16 E6 variants and have been oncogenic enhancers in cancer development through metabolic reprogramming." (PMID 38921041, 2024). "Therefore, an in-depth study on the role of HIF-1α in solid tumor malignancies is required to develop novel anti-cancer therapeutics." (PMID 38542288, 2024). "In cancer cells, Hif1α promoter is activated by NFκB subunits, mainly p5050." (PMID 39251668, 2024). "The HIF-1α pathway is known to play a critical role in both glycolysis and cancer stemness." (PMID 39300073, 2024). "HIF-1α drives several key mechanisms involved in the invasion of cancer cells." (PMID 39493156, 2024). "Compared with other E3 ligases that can either promote HIF1α’s degradation or stabilization, TRIM1 activates HIF-1α signaling by promoting its nuclear translocations instead of influencing the expression level, expanding the role of HIF1α ubiquitination in cancer." (PMID 38769340, 2024). "However, recent studies have revealed a close association between TME hypoxia and the development and metastasis of cancer cells, with hypoxia-inducible factor-1 alpha (HIF-1α) playing a key role in hypoxic adaptation." (PMID 38794281, 2024). "Likewise, mir-186 suppressed SP1, MYC, and HIF1A, and the induction of mir-186 induces the sensitivity of cancer cells to anticancer drug." (PMID 39590335, 2024). "The previous study reported that hypoxia-inducible factor 1α (HIF-1α) could activate PKM2 to participate in glucose metabolism reprogramming in cancer cells." (PMID 38409200, 2024). "In addition to maintaining the hypoxic environment of cancer cells to stabilize HIF-1α and activate its downstream target genes, CAF also regulate cancer cell metabolism through paracrine pathways." (PMID 38725864, 2024). "Myosin-1b (MYO1B) promotes cancer by targeting HIF1a and SNAI2/cyclinD160,61." (PMID 38291075, 2024). "It has been suggested that HIF-1α inhibition could be a therapeutic approach to treat cancer because of the role of HIF-1α in aerobic glycolysis and mitochondrial function." (PMID 39273552, 2024). "HIF1A acts as a major transcriptional driver in cancer progression." (PMID 38462658, 2024). "As such, targeting HIF-1α signaling has emerged as a promising strategy for cancer therapy." (PMID 38205087, 2024). "Additionally, in human breast cancer cells, silencing CD44 was also shown to decrease the glycolytic phenotype of cancer cells via regulating c‐Src/AKT/LKB1/AMPKα/HIF‐1α signaling." (PMID 38783892, 2024). "HIF1A and its transcriptionally regulated target genes are essential for cancer metastasis." (PMID 38902533, 2024). "Furthermore, both glycolytic co-activator proteins and glycolytic target genes of HIF-1α exhibited consistent demethylation patterns in cancer as well as residual cells, and isozyme-specific demethylation was present in either type of cells." (PMID 38413567, 2024). "Together, these findings suggest that CDK4/6 inhibitors may synergize with SMURF2’s role in degrading HIF1α, presenting a promising combination strategy to target hypoxic pathways in cancer therapy." (PMID 39697237, 2024). "In addition, the administration of allicin demonstrated a partial reversal of the effects generated by overexpression of HIF-1α, thus suggesting the protective function of allicin against cancer." (PMID 38542956, 2024). "In addition, both HIF-1α and YKL-40 serum levels above the cutoff value were independent risk factors for cancer recurrence in FTC patients." (PMID 39277981, 2024).
cancer (continued). "Thus, the crucial role of HIF1α in cancer progression has catalyzed the development of numerous inhibitors targeting its various functions, which are currently under investigation in preclinical and clinical stages." (PMID 39697237, 2024). "Interestingly, a previous in vitro study showed that HIF1α expression in various types of cancer cells changed after anesthesia." (PMID 39273283, 2024). "The upregulation of PDK1 by HIF-1α under hypoxic conditions is important for the inactivation of the pyruvate dehydrogenase complex, which switches glucose metabolism from oxidation to lactate formation in cultured fibroblasts and cancer cells." (PMID 39080182, 2024). "Glycolysis, a metabolic process controlled by HIF-1α, encompasses a series of enzymatic reactions and serves as the principal mechanism through which cancer cells produce adenosine triphosphate (ATP), the essential energy currency of cells, enabling their survival." (PMID 38792080, 2024). "We therefore sought to determine whether the upregulation of miR-210 induced by CD204+ M2-like TAMs is mediated by NF-κB and HIF-1α in cancer cells." (PMID 38175202, 2024). "USP7 has been proposed to deubiquitinate and stabilise HIF-1α in several cancer line cell types." (PMID 39584532, 2024). "In almost all cancers, the presence of a hypoxic environment increases HIF-1α expression." (PMID 39735605, 2024). "Hypoxia amplifies these conditions and stabilizes HIF-1α, enhancing the accumulation of oncometabolites deriving from the Krebs cycle and impairing DNA methylation to remodel intracellular environments optimal for cancer growth." (PMID 39195201, 2024). "A comprehensive understanding of this pathway may facilitate research aimed at identifying potential therapeutic targets to modulate the aberrant TNFR2/HIF-1α activity, which is crucial for the treatment of cancers including BC." (PMID 39609700, 2024). "HIF-1α plays a crucial role in cancer by influencing cell division and proliferation." (PMID 38399410, 2024). "Intriguingly, the existing literature posits that p-ERK might participate in the promotion of HIF-1α transcription in cancer cells under hypoxic conditions." (PMID 38339408, 2024). "Additionally, it activates AMPK signaling to disrupt energy homeostasis in cancer cells by downregulating intracellular concentrations of HIF1α and c-Myc." (PMID 38577616, 2024). "All these data imply that targeting HIF-1α and its signalling pathways in CAFs may provide different outcomes between different patients and cancers." (PMID 38352889, 2024). "In addition, in normoxic CRC cancer stem cells (CSCs), the expression of hypoxia-inducible factor 1-alpha (HIF-1α) was significantly reduced, leading to the restoration of PGC1α expression in these areas." (PMID 38774408, 2024). "However, the function of HIF-1α under normoxia is as important as that under hypoxia, as it can also effectively promote glycolysis and cancer stemness in cancer cells." (PMID 39300073, 2024). "HIF-1α mediating the reprogramming of the glucose metabolic pathway in cancer cells has become a characteristic of general attention, especially on the Warburg effect, making it a potential therapy to face the progression of cancers." (PMID 38472355, 2024). "The sensitivity of HIF1α to glucose could be a useful target for metabolic therapy, particularly in cancer treatment." (PMID 39466364, 2024). "AGPAT2, a direct target of HIF-1α, is elevated in cancer patient biopsies." (PMID 38399410, 2024). "The abnormal expression of HIF1A promotes the glycolysis process, including in cancer cells." (PMID 39193340, 2024). "HIF-1α mediates several survival mechanisms that allow cancer cells to withstand these challenges." (PMID 39493156, 2024). "In addition, the LPS-induced inflammatory environment promoted the expression of HIF-1a, thereby affecting metastasis in cancer." (PMID 38612546, 2024).
cancer (continued). "HIF-1α activates matrix metalloproteinases 1, 2, 9, and 14, aiding in the breakdown of extracellular matrix components and basement membrane degradation, thereby easing cancer cell migration and spread." (PMID 38799423, 2024). "Small molecule inhibitors targeting HIF-1α are a promising strategy in cancer therapy." (PMID 39493156, 2024). "Furthermore, resveratrol was able to inhibit the HIF-1α pathway, as previously shown in different studies focusing on cancer treatments." (PMID 38396755, 2024). "Though targeting hypoxic HIF-1α is a promising approach for cancer treatment, the benefit may be in a context-dependent or tissue-specific manner." (PMID 39125923, 2024). "Moreover, in interphase cancer cells and cardiomyocytes, transport of HIF-1α to the nucleus was reported to be mediated by an intact microtubule network and via dynein activity." (PMID 38300329, 2024). "Overall, the research into drugs targeting HIF-1α-related immune mechanisms could be of assistance in anti-cancer therapy." (PMID 37588219, 2024). "Therefore, cellular inability to inactivate the activity of HIF1α fosters the development of cancer." (PMID 39041636, 2024). "Therefore, the release of fatty acids by adipocytes and subsequently reuptake by cancer cells depends on the hypoxic HIF-1α pathway." (PMID 38236337, 2024). "Additionally, by disrupting HIF1α’s transcriptional activities, acriflavine has shown efficacy in melanoma cells by impairing pathways crucial for cancer cell survival, including angiogenesis and glycolysis." (PMID 39697237, 2024). "In hypoxic conditions or due to genetic alterations, the aberrant and excessive expression of HIF-1α plays a crucial role in cancer biology, as well as several other pathophysiological issues such as vascularization, angiogenesis, cell survival, other diseases, or oxidative stress." (PMID 38645491, 2024). "Thus, given the hypoxic nature of BC as a solid tumor, MDSCs are believed to be particularly active inside the TME, where they produce a significant amount of VEGF and other cancer-promoting molecular species in response to HIF-1α." (PMID 39609700, 2024). "Studies have reported that both STAT3 and HIF1-α can transcriptionally upregulate the expression of WTAP in some cancer cells, but we found that LPS-induced upregulation of WTAP was not affected by SC144 treatment, which inhibited the activation of STAT3 signaling by binding to IL6ST." (PMID 39007267, 2024). "However, for the first time, we relate the positive correlation between BAP31 and HIF-1α in cancer, specifically NB." (PMID 38474195, 2024). "GTE is known to inhibit hypoxia-induced HIF-1α protein accumulation in cancer cells by blocking the phosphatidylinositol 3-kinase/Akt and extracellular signal-regulated kinase 1/2 signaling pathways and elevating the protein degradation without affecting the mRNA expression." (PMID 38397833, 2024). "In addition, HIF1α and 2α seem to be working in concert with each other over longer periods of hypoxia to maintain the cancer stem cell pool." (PMID 39282472, 2024). "The percentage of HIF-1α-positive ICs in cancer can vary depending on the type of cancer." (PMID 39202223, 2024). "Our hypothesis was that changes in ACE2 expression following ropivacaine administration might induce changes in cancer cell biology via HIF1α and other pathways." (PMID 39273283, 2024). "Moreover, the loss of miR-125b and increased HIF-1α expression upregulate CD24 and erythropoietin, resulting in the enrichment of doxorubicin-resistant CD24+ cancer stem cell population." (PMID 39273339, 2024). "HIF-1α siRNA cancer therapy can utilize delivery systems based on whether the tumors are oxygen-deprived or not." (PMID 38399410, 2024). "ZMIZ1, a novel HIF-1α co-activator, has been shown to promote metastasis in cancer." (PMID 39334513, 2024). "As HIF1α is critical for cancer cell adaptation to hypoxia, oleic acid might indirectly help cancer cells survive hypoxia by increasing HIF1α translation." (PMID 39284708, 2024).